AIM2 (absent in melanoma 2)
Diseases named in the same sentence as AIM2 in open-access papers (continued):
Sharing a sentence is not in itself a finding about the gene and the disease.
lung diseases (1 paper, 2020). "Therefore, the novel approach for the development of the therapeutic agents belonging to the AIM2 inflammasome should be attempted by global scientists who have the passion to cure human lung diseases." (PMID 32121297, 2020). "The evidence for the importance of AIM2 inflammasome activation in IPF and other lung diseases could provide the necessity of developing therapeutic agents for the AIM2 inflammasome." (PMID 32121297, 2020).
memory impairment (1 paper, 2023). "Overall, these data demonstrated that C3aR‐A treatment ameliorated memory impairment in AIM2‐OE and aging mice." (PMID 37177836, 2023).
microcephaly (1 paper, 2021). A congenital or acquired developmental disorder in which the circumference of the head is smaller than normal for the person's age and sex. "Presence of NLRP1, NLRP3, and AIM2 together with elevated IL-1β, IL-18, and IL-33 could be detected in the brain of ZIKV-infected patients with microcephaly." (PMID 33796483, 2021).
migraine (1 paper, 2021). "Also the roles of NLRP1, NLRP2 and AIM2 inflammasome complexes needs further study in migraine and its comorbid diseases." (PMID 34112082, 2021).
mucocutaneous leishmaniasis (1 paper, 2025). The most common form of leishmaniasis that is transmitted through the bite of female phlebotomine sand flies or after exposure to leishmania parasites. "In particular, the high densities of NLRP3+, AIM-2+, and IL-1β+ cells found in the hyperreactive form of the disease suggest a role in exacerbating the inflammatory response in patients with mucocutaneous leishmaniasis (MCL)." (PMID 40431153, 2025).
Mycobacterium infection (1 paper, 2017). Infections with bacteria of the genus Mycobacterium. "In addition to cGAS and AIM2, we here established a role of another DNA sensor, IFI204, during mycobacterium infection." (PMID 28529930, 2017).
myelodysplastic syndrome (1 paper, 2022). A clonal hematopoietic disorder characterized by dysplasia and ineffective hematopoiesis in one or more of the hematopoietic cell lines. "Other very important participating factors, the NLRP3 and AIM2 inflammasomes, have appeared as crucial players in regulating certain hematological pathologies, e.g., myelodysplastic syndrome (MDS), MPNs, cardiovascular risk, and leukemia." (PMID 35328626, 2022).
myelofibrosis (1 paper, 2015). A partial or complete replacement of the bone marrow stroma by fibrous tissue. "Using D9 cells, we identified several genes involved in the inflammasome pathway, such as AIM2, IL1B, and CASP1, as downstream targets of JAK2V617F, which could explain the molecular mechanism behind myelofibrosis development in patients harboring the JAK2V617F mutation." (PMID 26823993, 2015).
myeloid leukemia (1 paper, 2024). A clonal proliferation of myeloid cells and their precursors in the bone marrow, peripheral blood, and spleen. "Thus, the AIM2-caspase-1 pathway drives ATRA+MRT-induced irreversible differentiation in myeloid leukemia cells." (PMID 38466568, 2024).
osteomyelitis (1 paper, 2022). An acute or chronic inflammation of the bone and its structures due to infection with pyogenic bacteria. "The increased expression of IL-1β and inflammasome-associated AIM2 as well as an implication of the Mitophagy pathway reported here supports the involvement of inflammasomes in the long-term infection leading to the development of osteomyelitis." (PMID 35531332, 2022).
osteoporosis (1 paper, 2025). A condition of reduced bone mass, with decreased cortical thickness and a decrease in the number and size of the trabeculae of cancellous bone (but normal chemical composition), resulting in increased fracture incidence. "The deletion of AIM2 and/or NLRP3 mitigated the bone loss caused by doxorubicin, shedding lights on the potential association of AIM2 inflammasome inhibitors with adjuvant therapy to limit the risk of osteoporosis and fractures in cancer patients treated with chemotherapy." (PMID 40002808, 2025).
periapical periodontitis (1 paper, 2021). Inflammation of the periapical tissue. "Increased IL-1β production in periapical periodontitis may be associated with the activation of NLRP3 and AIM2 inflammasomes." (PMID 34177950, 2021). "Collectively, canonical inflammasomes, such as NLRP3 and AIM2, and noncanonical inflammasomes may be involved in the pathogenesis and development of periapical periodontitis." (PMID 34177950, 2021).
Peritoneal Fibrosis (1 paper, 2019). Disorder characterized by a wide range of structural changes in PERITONEUM, resulting from fibrogenic or inflammatory processes. "In this regard, we observed no significant changes of these molecules in mice after MGO treatment; therefore, we assume that NLRP1, NLRC4, and AIM2 inflammasomes are less likely to be involved in MGO-induced peritoneal fibrosis." (PMID 31316105, 2019). "First, although we showed that NLRP3 deficiency significantly attenuates MGO-induced peritoneal fibrosis, we have not examined whether deficiency of other inflammasome-forming PRRs, such as NLRP1, NLRC4, and AIM2, could inhibit peritoneal fibrosis." (PMID 31316105, 2019).
peritonitis (1 paper, 2017). Inflammation of the peritoneum (tissue that lines the abdominal wall and covers most of the organs in the abdomen). "To assess the role of lentinan on AIM2 inflammasome activation, we adopted Listeria monocytogenes (LM)-induced peritonitis." (PMID 28465544, 2017).
PFAPA syndrome (1 paper, 2015). An auto inflammatory syndrome characterized by recurrent febrile episodes associated with aphthous stomatitis, pharyngitis and cervical adenitis. "DNA of patients with PFAPA syndrome was analyzed for the 3 genes associated with monogenic periodic fever (NLRP3, MEFV, and MVK) and for the AIM2 gene." (PMID 25821352, 2015). "Although no connection was identified between the AIM2 gene variants and PFAPA syndrome, it is still possible that epigenetic or somatic alterations of the gene could play a role in the disease onset." (PMID 25821352, 2015).
ptosis (1 paper, 2020). The drooping of the upper eyelid. "AIM2 and NLRP3 act as sensors to take part in the activation of caspase-1, which catalyzes neuroinflammation and ptosis." (PMID 32377306, 2020).
respiratory infections (1 paper, 2022). "During respiratory infections, the NLRP3 and AIM2 inflammasomes and caspase-11 protect against Brucella abortus through decreasing CFUs in the lungs and bronchoalveolar lavage fluid (BALF)." (PMID 35626718, 2022). "Specifically, ZBP1 interactions with NLRP3 and AIM2 inflammasomes are described in the context of the bacteria and viruses such as Francisella novicida and influenza virus, indicating the importance of ZBP1 in host–pathogen interactions during respiratory infection." (PMID 35626718, 2022).
retinal degeneration (1 paper, 2020). Degeneration of the retina. "Taken together, these results suggest a possible protective role for both adaptor protein ASC as well as AIM2 inflammasome sensor protein in retinal degenerations." (PMID 32041990, 2020). "Finally, in addition to investigations into NLRP3, the role of NLRC4 and AIM2 inflammasome sensor proteins in retinal degenerations was examined." (PMID 32041990, 2020). "We reasoned that inflammasome mediated-inflammation in retinal degenerations such as AMD may occur largely independently of NLRP3, NLRC4 or AIM2 sensor proteins." (PMID 32041990, 2020). "To identify whether inflammasome components in addition to CASP-1 might be responsible for the progression of retinal degenerations, we tested mice lacking NLRC4, AIM2 or ASC in our model of retinal degeneration." (PMID 32041990, 2020).
retinal detachment (1 paper, 2025). An eye emergency condition which may lead to blindness if left untreated. "As RPE-EMT is vital in the pathological progression of PVR, we investigated the effects of Aim2 deficiency on RPE-EMT in a retinal detachment (RD)-induced PVR mouse model." (PMID 39870644, 2025). "In a retinal detachment-induced PVR mouse model, AIM2 deficiency promotes RPE-EMT, resulting in severe experimental PVR." (PMID 39870644, 2025).
schizophrenia (1 paper, 2023). A major psychotic disorder characterized by abnormalities in the perception or expression of reality. "There is evidence that the cfDNA in patients with schizophrenia stimulated the expression of the TLR9 and STING genes while simultaneously blocking the expression of RIG-I and AIM2, which are involved in cfDNA sensing and activate the inflammatory response." (PMID 36834811, 2023).
small intestine cancer (1 paper, 2024). A primary or metastatic malignant neoplasm involving the small intestine. "The AIM2 gene contains a microsatellite instability site, potentially mutating in CRC and small intestine cancer." (PMID 38455052, 2024). "In addition, the AIM2 gene has microsatellite instability sites, leading to gene mutations related to CRC and small intestine cancer." (PMID 38455052, 2024).
Splenomegaly (1 paper, 2022). Abnormal increased size of the spleen. "However, 10-mo-old DNase II−/−Ifnar1−/− mice have been reported to develop splenomegaly and produce antinuclear antibodies in a STING- or AIM2-independent manner; instead, Unc93b, which regulates the localization of several TLRs (e.g., TLR3, TLR7, and TLR9) to the endosome, is required." (PMID 34901991, 2022).
Streptococcus pneumonia (1 paper, 2021). "We previously demonstrated that maturation and secretion of IL-1β require activation of AIM2 and NLRP3 inflammasome in Streptococcus pneumonia-infected macrophages and neutrophils." (PMID 34017331, 2021).
systemic candidiasis (1 paper, 2024). "To understand the role of AIM2 in defense against systemic candidiasis, we sourced bulk RNA-seq data from peripheral blood mononuclear cells (PBMCs) or monocyte-derived dendritic cells of healthy volunteers challenged ex vivo with C. albicans (GSE69723, GSE42606, GSE162746)." (PMID 38918243, 2024).
Ureteral obstruction (1 paper, 2025). Obstruction of the flow of urine through the ureter. "Immunofluorescence of kidney tissues isolated from patients with CKD displayed high levels of AIM2 and inflammation markers, whereas AIM2 deficiency attenuated renal inflammation and fibrosis in a mouse model of unilateral ureteral obstruction." (PMID 40264103, 2025).
viral myocarditis (1 paper, 2017). Myocarditis that is caused by an infection with a viral agent. "In the present study, the results show that AIM2 co-immunization with VP1 could mount long-lasting immune responses against acute viral myocarditis." (PMID 28642849, 2017).
vulvovaginal candidiasis (1 paper, 2016). Infection of the vulva and vagina with a fungus of the genus CANDIDA. "Does AIM2 also influence progression of vulvovaginal candidiasis?" (PMID 27592079, 2016).
ZIKV infection (1 paper, 2022). "One study also suggested that ZIKV can activate AIM2 inflammasome in skin fibroblasts, as elevated mRNA levels of AIM2 are induced by ZIKV infection, but more studies upon this should be performed." (PMID 36016430, 2022).
tumor (210 papers, 2008 to 2026). "The interplay between AIM2 and the tumor microenvironment also warrants attention, as AIM2 has been implicated in enhancing immune responses against tumor cells, potentially through the activation of pro-inflammatory cytokines like IL-1β." (PMID 40386782, 2025). "High levels of AIM2 in the tumor mass were associated with poor prognosis of NSCLC patients, defining two types of inflammatory profiles, which are inflammasome and non-inflammasome dependent." (PMID 39857785, 2025). "AIM2 is one of the tumor-associated antigens expressed by glioma cells, which specifically recognize and engage with the HLA-A1 locus." (PMID 40386782, 2025). "Nanoparticle-mediated delivery of the gene encoding AIM2 into renal cell carcinoma tissue also promotes caspase-1 activity and IL-1β secretion, leading to inhibition of tumor growth in mice." (PMID 41062723, 2025). "Therapeutic strategies to demethylate AIM2 or deliver AIM2-encoding vectors are being explored to restore its tumor-suppressive function." (PMID 40721869, 2025). "The loss of AIM2 expression in PCa cells is associated with increased tumor growth and metastasis, highlighting its importance in maintaining cellular homeostasis and preventing malignant transformation." (PMID 40386782, 2025). "In a study on AIM2-deficient mice, higher tumor development in the colon was observed following AOM/DSS treatment that induced AKT activation." (PMID 39684769, 2024). "A recent study found AIM2 inhibits BRAF mutated CRC growth via caspase-1 in vitro and in vivo, confirming AIM2 overexpression significantly inhibits BRAF-mutated CRC tumor growth and metastasis." (PMID 38455052, 2024). "This means that persistent inflammation induced by AIM2 overexpression attracts immunosuppressive cells, including regulatory T cells (Tregs), myeloid-derived suppressor cells (MDSCs), and tumor-associated macrophages (TAMs) at the tumor site." (PMID 38067304, 2023). "High expression of AIM2 is associated with poor prognosis of some tumor types, including KIRC, UVM, PAAD, and LGG." (PMID 36248785, 2022). "We further explored the association of AIM2 in cancer through prognosis analysis, immune infiltration analysis, methylation level analysis, and tumor purity." (PMID 36248785, 2022). "AIM2-deficient DC promoted tumor antigen–specific CD8+ T cell infiltration into the tumor via CXCL10." (PMID 35739593, 2022). "The results showed that either BCL2A1 or AIM2 staining was significantly associated with PSCC tumor progression, as indicated by clinical features including the pN status, clinical stage and ENE." (PMID 33391539, 2021). "The present study showed that the pyroptosis genes GZMA, AIM2, and PD-L1 were associated negatively, whereas the risk signature was associated positively with tumor stem cell scores." (PMID 34721986, 2021). "AIM2 expression was found to be significantly associated with tumor size (P = 0.006), LNM (P < 0.001) and TNM stage (P < 0.001)." (PMID 33859277, 2021). "In EBV‐associated NPC, EBV and irradiation‐induced AIM2 inflammasome activation lead to mature IL‐1β release that promotes tumor proliferation." (PMID 34014039, 2021). "AIM2 transcripts are specifically reduced in tumor tissue of paired liver biopsies from HBV-associated HCC." (PMID 33613561, 2020). "Chi-square test analysis showed that reduced AIM2 in CRC was significantly associated with tumor size (P=0.024), depth of invasion (P=0.011), LNM (P=0.001) and TNM stage (P=0.003)." (PMID 33291082, 2020). "In our previous study, we demonstrated that the release of IL-1α from lung tumor-associated plasmacytoid dendritic cells was AIM2 inflammasome dependent and promoted tumor cell proliferation in the lung." (PMID 29675024, 2018).
tumor (continued). "Research has revealed a notable decrease in AIM2 expression within GC tumor tissues, with AIM2 deficiency correlating with factors such as tumor size, lymph node metastasis (LNM), tumor, lymph node metastasis (TNM) stage, and unfavorable prognostic outcomes in GC patients." (PMID 39744568, 2025). "The role of AIM2 in tumor biology and the underlying mechanisms in various tumor types." (PMID 40386782, 2025). "Moreover, chemotherapy-induced AIM2 activation was associated with increased anti-tumor responses to anti-programmed cell death protein 1 (PD-1) therapy." (PMID 39857785, 2025). "For instance, the Wnt/β-catenin signaling pathway and upregulating autophagy-related genes (Bcl-2, Beclin-1 and ATG-5), have been implicated in RCC progression, and AIM2’s influence on these pathways could provide insights into its anti-tumor role." (PMID 40386782, 2025). "The correlation analysis of immune cell infiltration showed that CASP1, NLRP3, and AIM2, which showed that pyroptosis was involved in the infiltration of immune cells in the tumor microenvironment and NLRP1 exhibited high diagnostic efficacy, while PYCARD demonstrated poor diagnostic efficacy." (PMID 40026444, 2025). "The activation of the AIM2 inflammasome is involved in the establishment of an immunosuppressive lung microenvironment, the recruitment of T cells and plasmacytoid dendritic cells (pDCs), as well as the polarization of tumor-associated macrophages (TAM)." (PMID 40386782, 2025). "Moreover, AIM2 has been associated with different tumors subtypes wherein classically has been described as a tumor suppressor." (PMID 37819510, 2023). "Hence, AIM2-deficient DC vaccination not only enhances immune responses to the tumor by activating STING but also suppresses IL-1β and IL-18 production, resulting in synergistic therapeutic responses." (PMID 37046775, 2023). "AIM2 is more sensitive to stimulation with DNA-RNA hybrids compared to dsDNA, suggesting that both dsDNA and DNA-RNA hybrids can activate AIM2 inflammasome in tumor associated macrophages in the tumor microenvironment." (PMID 37449203, 2023). "Meanwhile, the AIM2 overexpression group was thinner than the control group, which may be caused by excessive tumor metastasis." (PMID 36923928, 2023). "AIM2 inflammasomes are closely associated with tumor development and prognosis." (PMID 36248785, 2022). "We further analyzed the association between AIM2 inflammasomes and tumor immunity." (PMID 36248785, 2022). "This study only provides preliminary findings that AIM2 inflammasomes are associated with tumor progression in a variety of tumors, and more experimental work is needed to determine the precise molecular function and mechanisms of AIM2 inflammasomes in tumorigenesis." (PMID 36248785, 2022). "Additionally, regulatory T cell (Treg) tumor infiltration was reduced, which was due to the loss of AIM2-dependent production of IL-1β and IL-18." (PMID 35432377, 2022). "Furthermore, the tumor‐promoting effects of the AIM2 inflammasome in EBV‐associated NPC can be reversed by neutrophil recruitment upon irradiation." (PMID 34014039, 2021). "Additionally, high levels of AIM2 are associated with strong tumor invasion through upregulation of the production of the invasion‐related proteinases MMP1 and MMP13 in cutaneous SCC." (PMID 34014039, 2021). "For example, GZMA and AIM2 gene expression in tumor cells was positively associated with increased drug sensitivity to nelarabine, dexamethasone decadron, fluphenazine, arsenic trioxide, procarbazine, olaparib, fludarabine, simvastatin, cyclophosphamide, and asparaginase." (PMID 34721986, 2021). "On the other hand, loss of AIM2 expression was observed in multiple tumor types including CRC." (PMID 33291082, 2020). "Loss of AIM2 expression correlated with advanced tumor stages and metastasis." (PMID 33613561, 2020).